IDH1 (isocitrate dehydrogenase (NADP(+)) 1)
Diseases named in the same sentence as IDH1 in open-access papers (continued):
Sharing a sentence is not in itself a finding about the gene and the disease.
CNS tumors (46 papers, 2013 to 2025). "Out of 12 patients with CNS tumors, positive results (Tier IA/IB) were found in 2 patients (1 men, 1 women), one of which had mutations in the IDH1 gene and the other in the NF1 gene." (PMID 39338229, 2024). "To date, the most crucial molecular marker of tumors of the CNS is IDH1/IDH2 mutations, the identification of which is an essential component of the diagnosis, characterization, and prognosis of diffuse gliomas." (PMID 37568598, 2023). "On the basis of the WHO 2016 classification of CNS tumors, 946 primary DGs were classified into 5 molecular subtypes through the integrated diagnosis of histological features and the status of IDH1/2 mutation and chromosome 1p/19q deletion." (PMID 36350010, 2022). "The 2016 WHO classification of CNS tumors is based on “integrated diagnosis” including histology and isocitrate dehydrogenase (IDH)-1/2 mutations (a biomarker for secondary GBM), and the presence of the 1p/19q codeletion (a marker for oligodendroglioma)." (PMID 32204305, 2020). "Although the 2016 WHO classification of CNS tumors suggested using IDH1 mutation status and chromosome 1p19q codeletion status to stratify LGG patients into clinically distinct subgroups, this classification still remains limited in prognosis predictions." (PMID 31861486, 2019). "The 2016 WHO classification of tumors of the CNS suggests the use of IDH1 mutation status and chromosome 1p19q codeletion status to predict the prognosis of LGG patients." (PMID 31861486, 2019). "Several follow-up studies encompassing thousands of central nervous system neoplasms have found similar frequencies of IDH1 and IDH2 mutations." (PMID 23847760, 2013). "IDH1/2 mutation status adopted into the WHO CNS Tumour Classification 2016." (PMID 37504251, 2023). "Mutations of IDH1/2 and codeletion of chromosomal 1p/19q were first introduced into the WHO classification of CNS tumors." (PMID 36350010, 2022). "Currently, the 2016 WHO classification of CNS tumors suggests the combined utilization of IDH1 status, 1p19q codeleted status, and histological subtypes to provide more objective diagnosis and classification of CNS tumors." (PMID 34439934, 2021). "This has prompted the 2016 WHO classification of CNS tumors to discriminate between IDH1-wildtype (IDH1-wt) and IDH1-mut GBMs." (PMID 30669568, 2019). "The absence of IDH1 or IDH2 mutations is an essential characteristic of GBM as defined in the 2021 WHO classification of CNS tumors." (PMID 40336841, 2025). "In summary, these examples highlight the impacts of CIC‐KO and IDH1‐R132H on enhancers at genes associated with CNS tumours and, regarding NFIA, illustrate an interesting case of an enhancer whose activity is differentially regulated by CIC loss in an IDH1‐dependent fashion." (PMID 34767259, 2022). "Herein, LGG patients were classified into three groups (Group 1: IDH1 wild-type, Group 2: IDH1 mutations with 1p19q codeletion, and Group 3: IDH1 mutations without 1p19q codeletion) according to the guideline of the 2016 WHO classification of CNS tumors." (PMID 34362400, 2021). "According to the guidelines of the 2016 WHO classification of CNS tumors, patients in the TCGA LGG cohort (n = 520) were classified into three groups for further analyses, including IDH1 wild-type, IDH1 mutations with 1p19q codeletion, and IDH1 mutations without 1p19q codeletion." (PMID 31861486, 2019). "The current WHO classification system for CNS tumors incorporates common genetic alterations, and diffuse gliomas are classified based on the presence or absence of mutations in the metabolic enzyme Isocitrate Dehydrogenase (IDH), the most common being IDH1-R132H." (PMID 38334611, 2024).
CNS tumors (continued). "According to the new 2021 WHO CNS tumor classification for GBM, we excluded IDH1-mutant patients from three GBM cohorts and further assessed the Loxl1-based model in IDH1-WT GBM cohorts." (PMID 38978755, 2024). "In the new 2016 WHO classification of CNS tumors, WHO grade III AAs are further divided into IDH1-mutant, IDH-wild type and NOS categories." (PMID 28978179, 2017). "Following the publication of the WHO CNS 4 classification guideline in 2016, researchers have identified several specific molecular markers including IDH1/2, EGFR, TERT, and MGMT that are relevant for survival and response to treatment in patients with CNS tumors." (PMID 37667984, 2023). "Importantly for the diagnosis of GBM, the determination of IDH1 mutation status has been included, resulting in distinct subgroups, namely, IDH1 mutant type (IDH1 MUT) and IDH1 wild type (IDH1 WT), since the 2016 WHO classification of CNS tumors was released." (PMID 36389748, 2022). "Despite our prognostic risk model being established in the previous GBM cohorts (IDH1 mutant and IDH1-WT), it showed a high performance in predicting the prognosis of GBM patients with IDH-WT that was redefined as GBM in the 2021 WHO classification of CNS tumors." (PMID 37284062, 2023). "Of note, 2 of the patients had IDH1-mutant tumors that would now be classified as astrocytoma, IDH-mutant, WHO grade 4, not as GBM, based on the WHO 2021 classification of tumors of the CNS." (PMID 39371261, 2024).
hematologic malignancies (19 papers, 2013 to 2025). "For these reasons, next‐generation sequencing (NGS) has become the standard for IDH1/2 mutation detection and quantification in many laboratories analyzing both solid tumors and hematological malignancies." (PMID 36062346, 2022). "In a sample of patients with IDH1-mutated advanced hematologic malignancies, plasma 2-HG levels were reduced by up to 99.7% after multiple doses of ivosidenib and were similar to those observed in healthy volunteers." (PMID 29882807, 2018). "Another Agios inhibitor AG 120 (Ivosidenib) is currently in phase III clinical trials for metastatic cholangiocarcinoma (NCT02989857) and advanced hematologic malignancies with IDH1 mutations (NCT02074839)." (PMID 29439493, 2018). "In a phase I/II study exclusively enrolling IDH1-mutated patients with advanced hematologic malignancies, the ORR was 38.5%, with 17.9% achieving a CR." (PMID 29795051, 2018). "In hematological disorders, mutations in IDH1 and IDH2 are occurring at a prevalence of 5–20% in de novo AML, and around 7.5% in de novo MDS patients." (PMID 29795051, 2018). "Bone marrow mononuclear cells from patients in another phase I study of ivosidenib in advanced hematologic malignancies were assessed for mutant IDH1 variant allele frequency to assess the depth of mIDH1 clearance." (PMID 29882807, 2018). "ivosidenib, an IDH1 inhibitor, induces apoptosis and has demonstrated clinical benefits in patients with various hematological malignancies." (PMID 41050081, 2025). "The specific inhibitor of IDH1, ivosidenib (AG-120), was evaluated for the first time in a clinical trial as a single agent in patients with IDH mutation-positive advanced hematologic malignancies." (PMID 30423907, 2018). "LY3410738 has recently entered clinical trials for the treatment of IDH1-mutant hematologic malignancies (NCT04603001) and IDH1-mutant solid tumors (NCT04521686)." (PMID 36056177, 2022). "Small molecule inhibitors targeting cellular oncoproteins and enzymes such as BCR-ABL, JAK2, Bruton tyrosine kinase, FLT3, BCL-2, IDH1, IDH2, are biomarker-driven chemotherapy-free agents approved for several major hematological malignancies." (PMID 33879198, 2021). "This indicates that IDH1 is one of the antitumor targets of GCN B and suggests that wild-type IDH1 may be a potential target for future intervention in hematologic malignancies." (PMID 36497259, 2022).
infection (13 papers, 2012 to 2026). The state of being infected such as from the introduction of a foreign agent such as serum, vaccine, antigenic substance or organism. "The association of IDH1 mutation with an increased risk of infection in the univariate analysis of this study is a noteworthy finding." (PMID 41347088, 2025). "To confirm that IDH1 mutation can regulate antiviral immune responses, we performed RNA sequencing (RNA-seq) in cells expressing IDH1(R132H) or a control vector upon VSVΔ51 infection." (PMID 37880243, 2023). "Remarkably, we also observed a reduction in abundance of host IDH1 upon infection with both species, suggestive of a possible impact on citrate accumulation as described for M1-like macrophages." (PMID 30895174, 2019). "Given the fact that these experiments were only performed after 20–24 h of stimulation and that the reduced activity of IDH1 is due to a decrease in its transcription, IDH1 might still be active during the early stages of infection." (PMID 29502308, 2018). "It is worth noting that IDH1(R132H) downregulated the total protein levels of IRF3/7 in cells either with or without VSVΔ51 infection." (PMID 37880243, 2023).
adenocarcinoma (6 papers, 2020 to 2025). A common cancer characterized by the presence of malignant glandular cells. "The SMAD4 mutation was associated with adenocarcinomas exhibiting mucinous morphology, which portends a poorer prognosis, while the most prevalent mutation of IDH1 is the R132C variant, which occurs in 20% of cases." (PMID 39199671, 2024). "In detail, one patient with adenocarcinoma harboring a missense point mutation in IDH1 (R132C) received ivosidenib as a third-line treatment, resulting in a progression-free survival (PFS) of 3.4 months." (PMID 38520742, 2024). "In this study, IDH1/2 mutations occurred in adenocarcinomas with high‐grade features and may be branching drivers leading to subclonal evolution." (PMID 32333643, 2020). "Multiregional analysis of an adenocarcinoma harboring two IDH2 mutations revealed parallel evolution originating from a KRAS‐mutated lineage, further supporting subclonal evolution promoted by IDH1/2 mutations." (PMID 32333643, 2020). "We evaluated IDH1/2 mutations in 1,924 NSCLC specimens (92% adenocarcinoma) using a next‐generation sequencing assay." (PMID 32333643, 2020).
Hematological cancers (5 papers, 2015 to 2025). "Homozygous missense mutations in both IDH1 or IDH2 have been described in several cancer types, including glioma, cholangiocarcinoma, and hematological tumors, such as AML and MDS." (PMID 31681423, 2019). "Hematological cancers are characterized by recurrent mutations in genes involved in the regulation of DNA methylation, notably TET2, IDH1/2 and DNMT3A." (PMID 25901663, 2015). "Taken together, these findings imply that combined inhibition of BTK and IDH1 along with IMiDs can be regarded as effective treatment strategies to enhance the efficacy against hematological cancer cells and offer an alternative way to tackle acquired resistance." (PMID 41050081, 2025).
blood cancers (4 papers, 2018 to 2025). "Mutant IDH1 has been extensively studied over the past decade and is an established clinical target in various brain and blood cancers." (PMID 37086156, 2023).
metabolic disease (3 papers, 2019 to 2025). A congenital disorder (due to inherited enzyme abnormality) or acquired (due to failure of a metabolically important organ) disorder resulting from an abnormal metabolic process. "Third, low levels of enrichment of 2HG are currently considered non-pathogenic, but this moiety is present in modest amount in metabolic disorders and in tumors that do not harbor IDH1/2 mutations." (PMID 39733217, 2025).
cardiovascular disease (2 papers, 2021 to 2023). "In this retrospective observational study, we investigated whether mutant IDH1/2 predisposes to cardiovascular disease in AML patients." (PMID 32948843, 2021).
gastrointestinal tumors (2 papers, 2016 to 2025). "We also identified two IDH1 mutations (two out of 17 ICC cases) that are known to be exclusive to ICC compared to other gastrointestinal tumors with potential diagnostic and therapeutic implications in ICC." (PMID 27009864, 2016). "The examination of mutations across various gastrointestinal tumors revealed that IDH1 or IDH2 mutations are specific to ICC and they may serve as druggable targets." (PMID 27009864, 2016).
cardiac disease (1 paper, 2021). "Notably, IDH1 and IDH2 mutations also occur as CHIP mutations and mechanistically lead to conversion of αKG to R-2HG, which is a proven oncometabolite and a potent inhibitor of TET2, suggesting a common pathway of CHIP induced cardiac disease." (PMID 32948843, 2021).
infectious disease (1 paper, 2025). A disorder directly resulting from the presence and activity of a microbial, viral, or parasitic agent in humans. "In addition, 3 died from infectious diseases at 1 month (VSAA with WTI variant), 3 months (VSAA with FLT3 variant), and 9 months (VSAA with ASXL1 and IDH1 variant) after diagnosis." (PMID 41477271, 2025).
neoplastic disorders (1 paper, 2024). "No monogenic disorder has been described for IDH1 in humans, although pathogenic IDH1 variants are common in human neoplastic disorders." (PMID 38397443, 2024).
IDH1 also shares sentences with these, for which no sentence is quoted: ependymoma (12 papers); lymphoma (7); Enchondromatosis (6); mental retardation (5); mental retardation syndrome X-linked (5); pleomorphic xanthoastrocytoma (4); central nervous system lymphoma (3); chondroblastoma (3); hereditary leiomyomatosis (3); Insulin resistance (3); mesenchymal tumors (3); primary myelofibrosis (3); primitive neuroectodermal tumor (3); sinonasal undifferentiated carcinoma (3); type 2 diabetes (3); uveal melanoma (3); acute kidney injury (2); anaplastic thyroid cancer (2); benign tumors (2); chronic lymphocytic leukemia (2); dementia (2); embryonal tumors (2); Ewing sarcoma (2); giant cell glioblastoma (2); giant cell tumor (2); head and neck cancer (2); head and neck squamous cell carcinoma (2); heart failure (2); inflammatory bowel disease (2); lung squamous cell carcinoma (2).
A further 106 diseases each share a sentence with IDH1 in 2 papers or fewer.